PKD1 (polycystin 1, transient receptor potential channel interacting)
Diseases named in the same sentence as PKD1 in open-access papers (continued):
Sharing a sentence is not in itself a finding about the gene and the disease.
bronchiectasis (3 papers, 2014 to 2023). Segmental, irreversible dilation of the bronchial tree resulting in the accumulation of secretions which leads to obstruction. "The aim of this study was to investigate the mechanism of bronchiectasis in ADPKD caused by PKD1 deficiency." (PMID 36309681, 2022). "By analyzing the PKD1 deficient pig lungs, we identified bronchiectasis and discovered that expression of E-cadherin was decreased in airway epithelial cells, which in turn promoted cellular barrier damage and an aggravated inflammatory response." (PMID 36309681, 2022). "Herein, by generating PKD1+/− pigs and a PKD1KD human lung epithelial cell line, we discovered that the deficiency of PKD1 caused impaired airway epithelial barrier functions and bronchiectasis." (PMID 36309681, 2022). "Thus, PKD1+/− pig is a suitable animal model in which to investigate the underlying mechanism of bronchiectasis." (PMID 36309681, 2022). "Thus, the deficiency of PKD1 in pig lung ciliated cells enhanced inflammation and mucus retention, which is similar to the clinical symptoms in bronchiectasis patients." (PMID 36309681, 2022). "Therefore, the ASM phenotype switch which drives bronchiectasis in PKD1+/− lungs is most likely contributed by the deficiency of PKD1 in airway cilia." (PMID 36309681, 2022). "The role of PKD1 in airway epithelial suggests a potential target for development of new strategies for the diagnosis and treatment of bronchiectasis." (PMID 36309681, 2022). "The alteration of extracellular matrix (ECM) components in PKD1+/− epithelial lead to an airway smooth muscle cell phenotype switch and resulted in airway remodeling and bronchiectasis formation." (PMID 36309681, 2022). "We identified bronchiectasis in PKD1+/− pigs, which is consistent with the clinical symptoms in ADPKD patients." (PMID 36309681, 2022). "Due to the impaired pathogen clearance and extracellular matrix deposition in the PKD1+/− lungs, airway smooth muscle cells undergo a switch from a contractile to a proliferative phenotype which drives airway remodeling and bronchiectasis formation." (PMID 36309681, 2022). "Drisco found decreased PKD1 expression in ADPKD lung compared to controls and hypothesized this leads to decreased ciliary function increasing the risk of bronchiectasis." (PMID 36615184, 2023). "Compared to control lungs, the H&E staining results showed that the area ratio of airway to adjacent artery was significantly increased whereas the value of wall area to lumen was decreased in PKD1+/− lungs, indicating that bronchiectasis occurred in the PKD1+/− pigs." (PMID 36309681, 2022). "In PKD1+/− pig lungs, examination of bronchiectasis development revealed a sequential process of epithelial and mesenchymal interactions that lead to airway remodeling and bronchiectasis." (PMID 36309681, 2022). "The PKD1+/− pig model provided a valuable tool to discover the mechanism of the progression of bronchiectasis, and the role of PKD1 in lung epithelial suggested a potential target to develop new strategy for the treatment of bronchiectasis." (PMID 36309681, 2022). "A proposed mechanism for the development of bronchiectasis in patients with ADPKD may be linked to abnormalities in polycystin-1 and 2, the gene products of PKD1 and PKD 2 located on chromosomes 16 and 4 respectively." (PMID 24747723, 2014). "Thus, in the current study, we investigated whether PKD1+/− pigs also suffered from bronchiectasis." (PMID 36309681, 2022).
dilated cardiomyopathy (3 papers, 2020 to 2024). Cardiomyopathy which is characterized by dilation and contractile dysfunction of the left and right ventricles. "Overexpression of constitutively active PKD1 in mouse hearts leads to dilated cardiomyopathy, and an increase in PKD1 expression and activity is seen in failing hearts of rats, rabbits and humans." (PMID 32351396, 2020).
glioma (3 papers, 2019 to 2025). A benign or malignant brain and spinal cord tumor that arises from glial cells (astrocytes, oligodendrocytes, ependymal cells). "Kaplan–Meier analysis of the overall survival (OS) rates showed that the OS rates for the low-expression group (PKD1-low) were significantly higher than those for the high-expression group (PKD1-high) (p < 0.001) in low-grade gliomas." (PMID 40299470, 2025). "To test the possibility of polycystins as a prognostic marker for glioma patients, we analyzed the PKD1 and PKD2 levels in the TCGA-glioma dataset." (PMID 40299470, 2025). "In addition, using public basis data, PKD1 and PKD2 emerged as prognostic factors in low-grade gliomas since the patients with low PKD1 or PKD2 expression display better overall survival compared with the patients with high PKD1 or PKD2 expression." (PMID 40299470, 2025). "The role of PKC and PKD1 in processes that are relevant to neoplastic transformation, proliferation, apoptosis, and tumor cell invasion provides a potential suitable target for anticancer therapy, including glioma." (PMID 31771098, 2019). "The state of knowledge on the expression and function of PKD in gliomas is limited, although recent studies have shown that ZKK3 inhibits the activity of PKD1 in glial cell lines as well as that of PKD isoforms under various tumour oxygen conditions." (PMID 35214064, 2022). "PKD1 and PKD2 expression were negatively correlated with the prognosis of glioma patients." (PMID 40299470, 2025). "Finally, PKD1 has been shown to regulate the sensitivity of U373MG glioblastoma cells to cis-platinum (CDDP), a common chemotherapy agent utilized to treat gliomas." (PMID 40299470, 2025).
hepatocellular carcinoma (3 papers, 2012 to 2023). A malignant tumor that arises from hepatocytes. "On the other hand, other groups proposed a potential tumor-suppressing role for PKD1, demonstrating that the overexpression of PKD1 in lung cancer cells, CRC, and hepatocellular carcinoma inhibited the invasion and migration of tumor cells." (PMID 37510333, 2023).
Infertility (3 papers, 2016 to 2025). "However, male patients carrying a pathogenic mutation in the Ig-like repeat domain of PKD1 had a high risk of infertility." (PMID 30333007, 2018). "Thus, male patients carrying pathogenic mutations in PKD1 located in the Ig-like repeat domain may have a high risk of infertility." (PMID 30333007, 2018). "Defects of the Ig-like repeat domain in PKD1 protein may alter its binding ability, leading to male reproductive tract cysts and infertility." (PMID 30333007, 2018). "PKD1-null mice develop multiple organ defects in the male reproductive tract and infertility." (PMID 27079378, 2016).
Insulin resistance (3 papers, 2020 to 2021). Increased resistance towards insulin, that is, diminished effectiveness of insulin in reducing blood glucose levels. "As described in the introduction, PKD1 overexpression protects against lipid-induced insulin resistance in the heart, but also induces the pathological condition of hypertrophic growth via HDAC5 phosphorylation." (PMID 33090289, 2021). "Indeed, PKD1 overexpression in cardiomyocytes in vitro or in the heart in vivo prevents the development of lipid-induced insulin resistance." (PMID 33090289, 2021). "Hence, as a future step in therapeutic strategies against lipid-induced insulin resistance, specific PKD1 activators could be employed to coerce myocytes to specifically take up glucose for subsequent v-ATPase reassembly." (PMID 32102213, 2020). "The specific PKD inhibitor CRT0066101 or PKD1 knockdown can eliminate the inhibitory effect on AMPK, illustrating that PKD1 inhibitor restores AMPK signaling to abolish insulin resistance in muscle cells." (PMID 34249722, 2021). "Furthermore, the protective effect of PKD1 overexpression on lipid-induced insulin resistance is mediated via PI4KIIIβ, since it was absent in the presence of MI14." (PMID 33090289, 2021).
ischemic stroke (3 papers, 2014 to 2025). A stroke disorder caused by obstruction of blood flow to the brain, due to thrombotic (local blood clot formation) or embolic (due to a blood clot or other material traveling from another site) event. "The serine/threonine protein kinase D1 (PKD1) confers neuroprotection in various neuropathological conditions, including ischemic stroke." (PMID 40461488, 2025). "Our findings indicated that PKD1 activity, and consequently this neuroprotective pathway, is suppressed by excitotoxicity in both in vitro models and in vivo models of ischemic brain damage, as well as in human ischemic stroke patients." (PMID 40461488, 2025). "In conclusion, these novel findings reveal a crucial role of PKD1 in the regulation of nNOS activation and synthesis of ·NO, a mediator involved in physiological neuronal signaling or neurotoxicity under pathological conditions such as ischemic stroke or neurodegeneration." (PMID 24740233, 2014). "Collectively, our results strongly suggest that the PKD1/IKK/NF-κB pathway is constitutively “on” in healthy neurons and suffers an early and sustained “shut-off” in human brain after ischemic stroke and in experimental models of excitotoxicity and brain ischemia." (PMID 29273751, 2017).
lymph node metastasis (3 papers, 2018 to 2024). "Additionally, PKD1 was also found to be downregulated in non-small cell lung cancer patients with venous invasion or lymph node metastasis and loss of PKD1 enhanced the malignant potential of the tumor cells, possibly by negative regulation of mTORC1–S6K1 signaling." (PMID 33807058, 2021). "Interestingly, in a small cohort of metastases (15 lymph node metastases and one liver metastasis), a significant reduction of PKD1 expression was observed in distal metastases as compared to the localized primary tumors (p = 0.002), suggesting a reverse correlation with tumor metastasis." (PMID 30419840, 2018). "PKD1 status did not correlate with sex (p = 0.90), smoking (p = 0.68), alcohol consumption (p = 0.75), tumor size (p = 0.52), lymph-node metastasis (p = 0.21), distant metastasis (p = 0.37), p16INK4a status (p = 0.26), HPV infection (p = 0.49) or PKD3 status (p = 0.36)." (PMID 39408603, 2024).
osteoporosis (3 papers, 2017 to 2026). A condition of reduced bone mass, with decreased cortical thickness and a decrease in the number and size of the trabeculae of cancellous bone (but normal chemical composition), resulting in increased fracture incidence. "Primary cilia containing PKD2/PC2 and PKD1/PC1 operate as osteoporosis-related mechanoreceptors in osteoblasts and renal epithelial cells, and BICC1 has been found in renal cell primary cilia." (PMID 35756494, 2022). "This suggests that Pkd1 knockdown, specifically in osteoclasts, results in diminished bone resorption activity and unaffected bone formation, a change that may be beneficial in preventing osteoporosis or improving bone strength." (PMID 41602825, 2026). "Our findings using the PKD1 mutant mice have paved the way for systematic analysis of PKD in bone-related pathological conditionsand provided further support for developing novel PKD-targeted therapeutic conditions such as fracture healing and osteoporosis in a potentially cost-effective treatment." (PMID 28084409, 2017).
osteosarcoma (3 papers, 2013 to 2018). A usually aggressive malignant bone-forming mesenchymal neoplasm, predominantly affecting adolescents and young adults. "Overexpression of PKD1 has also been shown to suppress the growth of osteosarcoma xenografts in vivo." (PMID 30419840, 2018). "Overexpression of PKD1 inhibits osteosarcoma cell proliferation, invasion, and migration and reduced matrix metalloproteinase 2 (MMP2), while knockdown of PKD1 has the opposite effects." (PMID 30419840, 2018). "In human osteosarcoma, PKD1 expression in osteosarcoma is significantly lower than that in benign schwannoma samples, and the expression pattern correlated with metastatic potential." (PMID 30419840, 2018).
Pancreatic cysts (3 papers, 2009 to 2024). A cyst of the pancreas that possess a lining of mucous epithelium. "First, the presence of pancreatic cysts, 2 mm or larger, predicts the greater likelihood of the PKD2 over the PKD1 mutation." (PMID 39058059, 2024). "Patient ID#64 had diagnosis of renal and pancreatic cysts at age 2 years, with recurrent infections and was found to have two VUS in PKD1, inherited in trans from healthy parents." (PMID 38177409, 2024).
polycystic kidney disease 2 (3 papers, 2014 to 2025). Autosomal dominant polycystic kidney disease caused by a mutation in PKD2. "The majority of ADPKD cases are due to mutations in the genes polycystic kidney disease 1 (PKD1) and polycystic kidney disease 2 (PKD2), which encode for polycystin-1 (PC1) and polycystin-2 (PC2) protein, respectively." (PMID 38474131, 2024).
rheumatoid arthritis (3 papers, 2019 to 2026). A chronic, systemic autoimmune disorder characterized by inflammation in the synovial membranes and articular surfaces. "We investigated whether TLR/IL-1R ligands can activate PKD1 and whether PKD1 plays a role in TLR/IL-1R-mediated proinflammatory gene expression in human fibroblast-like synoviocytes isolated from donor without rheumatoid arthritis (HFLS-N) or with rheumatoid arthritis (HFLS-RA)." (PMID 31809526, 2019).
alveolitis (2 papers, 2014 to 2024). "Similar to what was observed in PKD1-insufficient mice, repeated exposures of PKD1mKO to S. rectivirgula resulted in significantly reduced alveolitis and suppressed granuloma formation in the lungs compared with those in WT mice." (PMID 39464896, 2024). "However, the reduction in alveolitis in PKD1mKO appears less than that in PKD1-insufficient mice previously reported." (PMID 39464896, 2024). "Additionally, we investigated whether PKD1 in myeloid cells contributes to the neutrophilic/lymphocytic alveolitis and the cytokine/chemokine milieu that affects the pulmonary accumulation of pathogenic Th1 and Th17 cells during the development of HP caused by repeated exposure to S. rectivirgula." (PMID 39464896, 2024). "It has been recently shown that PKD1 is essential for TLR ligand-induced macrophage activation and cytokine production and that PKD inhibition suppresses microbial Ag-induced hypersensitivity pneumonitis in mice." (PMID 25000413, 2014). "Moreover, it has been shown that PKD1 is a key modulator of macrophage activation by toll-like receptors (TLRs) and that PKD inhibition suppresses microbial Ag-induced hypersensitivity pneumonitis in mice." (PMID 25000413, 2014).
aneurysm (2 papers, 2018 to 2022). Bulging or ballooning in an area of an artery secondary to arterial wall weakening. "Significantly, in the subgroup of patients who experienced aneurysms, 10 (58.8%) patients had a non-truncant PKD1 mutation, 3 (17.6%) had a truncant PKD1 mutation, 1 (5.9%) carried a different mutation from PKD1 or PKD2, and the genetic analysis of 3 (17.6%) was unavailable." (PMID 34586427, 2022).
Bartter syndrome (2 papers, 2020). "Production of pathologic proteins regulated by defective genes in exosomes from certain genetic renal diseases may be either decreased (PKD1 in ADPKD) or totally absent (SLC12A1 in Bartter syndrome type 1)." (PMID 32849923, 2020).
Caroli disease (2 papers, 2014 to 2022). Caroli disease (CD) is a rare congenital liver disease characterized by non-obstructive cystic dilatations of the intra-hepatic and rarely extra-hepatic bile ducts. "A mutation of the exon 46 (12801de128) of the PKD1 gene was associated with Caroli disease and PKD1 phenotype in two family members." (PMID 35741793, 2022). "Comparing the WES findings with the different phenotypes of the twins, we determined whether any variants in genes related to Caroli disease, hepatic function, or kidney function could act as a genetic modifier for Caroli disease (such as NPHP3, PKD1 and so on)." (PMID 24710345, 2014).
coronary artery disease (2 papers, 2018 to 2019). "PKD1 has been identified as a novel risk gene for coronary artery disease in patients suffering from type 1 diabetes, according to a genome-wide association study." (PMID 31757932, 2019).
diabetic kidney disease (2 papers, 2023 to 2024). Progressive kidney disorder caused by vascular damage to the glomerular capillaries, in patients with diabetes mellitus. "While PKD1 is involved in the maintenance of renal epithelial differentiation and organization, single nucleotide polymorphisms in the COL20A1 locus are associated with diabetic kidney disease." (PMID 38093359, 2023).
early onset hypertension (2 papers, 2020 to 2024). A form of hypertension with early onset relative to normal range for a given population. "In an unrelated analysis of patients with severe early-onset hypertension in 100KGP, we found PKD1 to be the most strongly associated gene on collapsing analysis, with many of the cases having been solved." (PMID 39190485, 2024).
endothelial dysfunction (2 papers, 2018 to 2025). In vascular diseases, endothelial dysfunction is a systemic pathological state of the endothelium (the inner lining of blood vessels) and can be broadly defined as an imbalance between vasodilating and vasoconstricting substances produced by (or acting on) the endothelium. "Recently endothelium-specific mutations in Pkd1 and Pkd2 were shown to independently cause endothelial dysfunction in mice." (PMID 40722835, 2025). "Thus, mutations of PKD1 contribute to endothelial dysfunction via decreased migration and increased endothelial permeability." (PMID 29472562, 2018).
Glucose intolerance (2 papers, 2021 to 2025). Glucose intolerance (GI) can be defined as dysglycemia that comprises both prediabetes and diabetes. "At first glance, these findings appear to contradict a previous study in which β-cell-specific knockout of PKD1 exacerbated HFD-induced glucose intolerance." (PMID 41349796, 2025).
Hypocalcemia (2 papers, 2023 to 2024). An abnormally decreased calcium concentration in the blood. "Inducible kidney‐specific Pkd1 knockout mice (iKsp‐Pkd1−/−) exhibit hypocalcemia and hypomagnesemia in a precystic stage and show increased expression of the ATP‐release channel pannexin‐1." (PMID 38561249, 2024). "We have previously demonstrated that inducible kidney‐specific Pkd1 knockout mice (iKsp‐Pkd1−/−) demonstrate hypomagnesemia and hypocalcemia in the precystic stage." (PMID 38561249, 2024). "However, the observed reductions in serum Mg2+ and Ca2+ concentrations in precystic iKsp‐Pkd1−/− mice are relatively modest and may not result in symptoms associated with hypomagnesemia and hypocalcemia." (PMID 38561249, 2024). "In conclusion, we show here that administration of BB‐FCF did not correct the hypomagnesemia and hypocalcemia in iKsp‐Pkd1−/− mice." (PMID 38561249, 2024). "In the current study, we show that pannexin‐1‐dependent ATP release is unlikely to explain the hypomagnesemia and hypocalcemia in iKsp‐Pkd1−/− mice." (PMID 38561249, 2024).
insulinoma (2 papers, 2009 to 2025). "In the INS-1 rat insulinoma β-cell line, PKD1 promotes insulin granule biogenesis and secretion at the TGN, a process negatively regulated by p38δ." (PMID 41349796, 2025). "HA pulldowns also contained endogenous PKD1 in INS1 cells (rat insulinoma-derived pancreatic β cell line) stably expressing HA-p38δF324S but not in cells expressing HA alone." (PMID 19135240, 2009). "However, direct examination of PKD1 function in β-cells has been carried out almost exclusively in the rat insulinoma cell line INS-1." (PMID 41349796, 2025).
lung carcinoma (2 papers, 2021 to 2023). "PKD1 also regulates cell proliferation and cell migration through mammalian target of rapamycin (mTOR) and Janus kinase (JAK) signals, but in the lung cancer cell line (A549), PKD1 inhibits cell migration and functions as a tumor-suppressor protein in some cases." (PMID 34064452, 2021).